ENSG00000272647 (novel protein)
Gene: Protein-coding gene on chromosome 7 (99,558,695 to 99,607,810, forward strand). Ensembl gene ENSG00000272647.
Genetic constraint (gnomAD): Missense variants: 117 observed, 127.9 expected, observed/expected ratio (o/e) 0.91, 90% interval 0.79 to 1.07. Synonymous variants: 27 observed, 48 expected, observed/expected ratio (o/e) 0.56, 90% interval 0.41 to 0.78.